CXCL12 (C-X-C motif chemokine ligand 12)
Diseases named in the same sentence as CXCL12 in open-access papers (continued):
Sharing a sentence is not in itself a finding about the gene and the disease.
lupus (continued). "In addition to highlighting the unique interest of using soluble ligands, here CXCL12, as potentially valuable drug targets, the results underline the importance of the CXCL12/CXCR4 axis in lupus pathophysiology." (PMID 34744730, 2021). "In the present study, we provide novel insights into the CXCL12/CXCR4 axis biology in lupus." (PMID 34744730, 2021). "Altogether, our data strongly suggest that autoreactive IgE, PGD2, and CXCL12 may synergize to amplify basophil accumulation in SLOs and their contribution to lupus pathogenesis." (PMID 29463843, 2018). "Interestingly, lupus mice infected with live malaria parasite exhibited a significant reduction in CXCL12-mediated actin polymerization compared with the lupus group (# P < 0.05, n = 5)." (PMID 25909640, 2015). "Moreover, a recent study reported that the CXCR4/CXCL12 axis controls auto-immunity in lupus patients following influenza vaccine." (PMID 25909640, 2015). "CXCR4 and its ligand CXCL12 may take over as suggested by the beneficial effect of a CXCR4 antagonist peptide in another mouse model of lupus (B6.Sle1Yaa;)." (PMID 23520491, 2013). "Furthermore, in lupus-prone NZB/W mice, increased renal CXCL12 expression is closely associated with nephritis and autoantibody production, and administration of anti-CXCL12 monoclonal antibodies has been shown to effectively prevent the development of nephritis." (PMID 41601976, 2026). "LIT-927 behaves as a “neutraligand” that interacts directly with the chemokine CXCL12 and could block it before it crosses the blood brain barrier known to be leaky in neuropsychiatric forms of lupus or before it reaches its targets in the kidneys, for example." (PMID 34744730, 2021). "Some studies pioneered this field to some extent and notably pointed out the importance of the CXCL12/CXCR4 pathway in systemic lupus erythematosus (SLE) physiopathology." (PMID 34744730, 2021). "MRL/lpr lupus-prone mice were treated with the DPP-4 inhibitor linagliptin, either alone or in combination with the CXCL12/CXCR4 axis antagonist AMD3100." (PMID 41601976, 2026). "In animal models, lupus-prone mice exhibit high CXCR4 expression in B cells, monocytes, neutrophils, and plasma cells, along with significantly elevated CXCL12 levels in the glomeruli and tubules." (PMID 41601976, 2026). "As a result of these findings, CXCL12/CXCR4 interactions play a crucial role in numerous physiological processes and are likely to significantly impact pathological conditions such as lupus." (PMID 39070795, 2024). "Investigations performed by different groups demonstrated variable results regarding possible changes in the expression levels of CXCL12 and CXCR4 in lupus." (PMID 34744730, 2021). "In the same vein, expression levels of CXCL12 and its two cognate receptors CXCR4 and CXCR7 have been found to be altered in SLE patients and murine models of lupus." (PMID 34744730, 2021). "Perhaps the most prominent effect was in its normalization of plasma cytokines, several of which, such as CCL5/RANTES, CXCL2/MIP-2, CXCL12/SDF-1α, and CXCL13/BCA-1, were known biomarkers of lupus severity." (PMID 32582860, 2020). "In several lupus models, CXCR4 expression is increased in B cells, plasma cells, T cells, neutrophils, and monocytes, which concurs with the increased CXCL12 expression in the kidney." (PMID 31507535, 2019). "The other chemokine member, CXCL12 and its receptor CXCR4, have been shown to be markedly elevated in infected lupus mice via activation of the NF-κB signaling pathway." (PMID 26310926, 2015). "Because the B cells of lupus mice exhibited high expression levels of CXCR4, we monitored the B cell responsiveness to CXCL12 in term of actin polymerization, chemotaxis, proliferation and signaling." (PMID 25909640, 2015).
lupus (continued). "Altogether, these data illustrate that in lupus, major alterations occur in the CXCL12/CXCR4 axis, and suggest that measuring the expression levels of CXCL12 and/or CXCR4 could be useful to follow the activity status of patients." (PMID 34744730, 2021). "To conclude, our present results suggest that by hampering the interaction between CXCL12 and CXCR4, the LIT-927 neutraligand limits the signaling occurring into T and B cells in lupus context with potential favorable outcome on the course of the lupus disease that needs further investigations." (PMID 34744730, 2021). "In the present study, we demonstrate that basophils from SLE patients and lupus-prone mice were able to migrate towards a CXCL12 gradient, unlike their healthy counterparts." (PMID 29463843, 2018). "Moreover, basophils from lupus-prone mice and patients with SLE have a specific sensitivity to CXCL12." (PMID 29463843, 2018). "Importantly, both CXCL12 and CXCR4 expressions are increased in the kidney of diseased lupus-prone mice, indicating migration of CXCR4+ cells into the kidney as LN progresses." (PMID 27403037, 2016). "In contrast, when compared throughout the stimulation time, treating lupus mice with gamma-irradiated malaria parasite did not affect CXCL12-mediated actin polymerization compared with the lupus group." (PMID 25909640, 2015). "We observed that lupus mice infected with live malaria parasite, but not gamma-irradiated malaria parasite, exhibited a significant reduction in CXCL12-mediated actin polymerization compared with the non-lupus control group." (PMID 25909640, 2015). "In the validation set GSE7305, CXCL12, ROBO3, and SCG2 were significantly enriched in immune-related pathways, including cytokine-cytokine receptor interaction, chemokine signaling pathway, leukocyte transendothelial migration, systemic lupus erythematosus, and MAPK signaling pathway." (PMID 38035102, 2023). "In lupus-prone mouse models, CXCR4 is consistently increased in various immune cell populations including B cells, plasma cells, T cells, neutrophils, and monocytes in the circulation and spleen of diseased mice, suggesting enhanced chemotaxis of these cells towards CXCL12." (PMID 27403037, 2016). "Additionally, the lupus mouse infected with live (green histogram), but not gamma-irradiated malaria (blue histogram) parasite, exhibited a marked restoration in CXCL12-mediated actin polymerization." (PMID 25909640, 2015). "CXCL12 is upregulated in the tubules and glomeruli of nephritic kidneys from multiple lupus-prone mouse models (e.g. NZB/W, BXSB, MRL.lpr) and SLE patients as well." (PMID 23244336, 2012). "Furthermore, the B cells of lupus mice exhibited an increased proliferative capacity; aberrant overexpression of the chemokine receptor CXCR4; and a marked elevation in responsiveness to their cognate ligand (CXCL12) via aberrant activation of the PI3K/AKT, NFκB and ERK signaling pathways." (PMID 25909640, 2015). "The activity of CXCL12 neutraligands, and of LIT-927 in particular, has not been studied previously in the context of animal models of lupus and systemic autoimmunity in general." (PMID 34744730, 2021). "The study was extended to the expression of CXCR7, which is another receptor for CXCL12 but, unlike CXCR4, it has never been investigated in the context of lupus pathogenesis." (PMID 23244336, 2012). "Interestingly, infecting lupus mice with live but not gamma-irradiated malaria parasite restored a normal proliferative capacity, surface expression of CXCR4 and B cell response to CXCL-12." (PMID 25909640, 2015).
acute lymphoblastic leukemia (26 papers, 2012 to 2025). Leukemia with an acute onset, characterized by the presence of lymphoblasts in the bone marrow and the peripheral blood. "At least in acute lymphoblastic leukemia, Rac1 activation is observed in response to the CXCL12/CXCR4 axis." (PMID 36009428, 2022). "An early study using adoptive transfer of the Nalm6-GFP preB Acute Lymphoblastic Leukemia (ALL) cell line found reduced Cxcl12 expression in poorly-defined bone marrow niches, resulting in displacement of normal hematopoietic stem and progenitor cells." (PMID 33324418, 2020). "Specifically, Nalm-6 pre-B acute lymphoblastic leukemia cells (ALL) have been reported to metastasize to CXCL12+ vascular niches in the BM due to their pronounced sensitivity to the chemoattractive cues of CXCL12." (PMID 28423491, 2017). "In addition, the receptor GPR30 was reported to mediate CCL18 inhibition of CXCL12-stimulated chemotaxis on pre-B acute lymphocytic leukemia cells." (PMID 39259753, 2024). "In vivo imaging of bone marrow using a custom-built fluorescence confocal/multiphoton microscope revealed that pre-B-cell acute lymphoblastic leukemia (ALL) cells preferentially home to bone marrow vessels that express the adhesion molecule E-selectin and Cxcl12." (PMID 28660186, 2017). "Consistent with a lack of agonistic function, a CXCR4-expressing murine acute lymphoblastic leukemia (ALL) cell line, which strongly releases Ca++ upon stimulation with CXCL12, showed no Ca++ release upon GPR15LG treatment." (PMID 40394646, 2025). "In the BM of a severe combined immunodeficiency (SCID) mouse model with a pre-B acute lymphoblastic leukemia (ALL), they demonstrated that both normal HSCs and leukemic stem cells (LSCs) localize to specific vascular niches enriched with stromal cell-derived factor-1 (SDF-1)/CXCL-12." (PMID 31485227, 2019).
bladder cancer (25 papers, 2009 to 2025). "This pattern is consistent with findings in human bladder cancer, where CXCL12-positive stroma is associated with increased T cell infiltration." (PMID 40849508, 2025). "In the context of bladder cancer, cancer-associated fibroblasts (CAFs) secrete CXCL12, which activates the JAK2/STAT3 signaling pathway, leading to the accumulation of p62." (PMID 38920657, 2024). "Several chemokines within the CXCL family, such as CXCL1, CXCL2, CXCL5, CXCL8 (IL-8), and CXCL12, also play a crucial role in the recruitment of myeloid cells and TAM in bladder cancer, and are associated with tumor grading, staging, and metastasis." (PMID 39606239, 2024). "CAF-derived CXCL12 enhances the immune evasion of bladder cancer by inhibiting P62-mediated autophagic degradation of PD-L1, thereby promoting the growth of bladder cancer cells." (PMID 39742262, 2024). "For example, activation of STAT3 mediated CXCL12 upregulation in the dorsal root ganglion and was essential for CXCL12-induced cell invasion in bladder cancer." (PMID 38338982, 2024). "The effects of CXCL12 on bladder cancer progression were investigated through in vitro and in vivo assays." (PMID 38001512, 2023). "Next, we stimulated mouse bladder cancer cell MB49 with recombinant mouse CXCL12 prior to animal experiments." (PMID 38001512, 2023). "Conversely, inflammatory CAFs, which secrete CXCL12 and IL-6 in bladder carcinoma, are essential for inducing a bladder carcinoma tumor-immunosuppressive microenvironment and promoting bladder carcinoma progression." (PMID 37853464, 2023). "ELISA results of culture medium (CM) showed that CAFs secreted CXCL12 at the highest level, followed by NF at a lower level, while bladder cancer cells only secreted trace amounts." (PMID 38001512, 2023). "We demonstrated that CXCL12 was a key prognostic cytokine secreted mainly by CAFs in TME of bladder cancer." (PMID 38001512, 2023). "In conclusion, high expression of ADRA2A, CXCL12, S1PR1, ADAMTS9, F13A1, and SPON1 was associated with poor overall survival in bladder cancer patients, with a P-value <0.05 considered to be statistically significant." (PMID 32239176, 2020). "Exposure of bladder cancer cells expressing CXCR4 to CXCL12 (the cytokine known as stromal cell-derived factor-1) leads to cell migration and invasion of the extracellular matrix." (PMID 19719844, 2009). "Both in vivo and in vitro experiments confirmed that CXCL12 could promote the proliferation, invasion and migration of bladder cancer cells, which is consistent with the findings of previous studies." (PMID 38001512, 2023). "In this study, we highlight a novel role of CXCL12 in the regulation of PDL1 in bladder cancer." (PMID 38001512, 2023). "The role of CXCL12 in the pathogenesis of bladder cancer has been widely reported." (PMID 38001512, 2023). "In addition, EGFP-mCherry-LC3 plasmid was transfected into bladder cancer cells to visualize the effect of CXCL12 on autophagy." (PMID 38001512, 2023). "The results of MTT assay, Wound-healing assay and transwell invasion assay showed that CXCL12 significantly promoted the proliferation, migration and invasion abilities of bladder cancer, and its antagonist AMD3100 was effective in reversing this supportive effect." (PMID 38001512, 2023). "Targeting CAFs-derived CXCL12 may provide an effective strategy for immunotherapy in bladder cancer." (PMID 38001512, 2023). "In-depth study of CAFs will further elucidate the pathogenesis of bladder cancer, and targeting CAFs-derived CXCL12 may provide a potential therapeutic strategy for bladder cancer." (PMID 38001512, 2023). "Moreover, FN1, CXCL12, CD3E, LCK, and ZAP70 were key interconnected node genes in PPI networks and are also associated with overall survival in patients with bladder cancer." (PMID 33204728, 2020). "The CXCR4/CXCL12 axis appears crucial in the metastasis of bladder cancer." (PMID 19719844, 2009).
bladder cancer (continued). "Our work revealed the prognostic value of CAFs in bladder cancer and the positive regulation of PDL1 by CAFs-derived CXCL12." (PMID 38001512, 2023). "Moreover, CXCL12 could be an indicator of bladder cancer microenvironment modulation." (PMID 35468838, 2022). "CCX733 is a selective CXCR7 antagonist that reduces the antiapoptotic effects of CXCL12 in glioma cells and CXCR7-induced EMT in bladder cancer." (PMID 33363463, 2020). "Together, this study identified four prognostic hub immune-related genes, including MMP9, IGF1, CXCL12 and PGF, which might play a vital role in bladder cancer development." (PMID 32675942, 2020). "CXCL12 and CXCR4 are not expressed in normal bladder tissue, but exhibit highly expression in bladder carcinomas." (PMID 39606239, 2024).
heart failure (25 papers, 2011 to 2025). Inability of the heart to pump blood at an adequate rate to meet tissue metabolic requirements. "More general biomarkers related to heart failure and increased all-cause mortality risk include stromal cell-derived factor 1α (SDF-1) which CXCL12 encodes." (PMID 38136253, 2023). "Recently, it was shown that CXCL12 is also associated with heart failure, and that plasma CXCL12 levels are even superior to ­traditional risk factors in predicting adverse cardiovascular outcomes." (PMID 26257740, 2015). "Indeed, increased CXCL12 levels were associated with increased risk of heart failure and CAD severity." (PMID 40986007, 2025). "CXCL-12 (stromal cell-derived factor 1, SDF-1) is another cytokine associated with PACS that is involved in tissue healing, immunological cell trafficking, cancer, and heart failure." (PMID 39200115, 2024). "In the present study, sunitinib upregulated TGF-β, IL-1, IL6, IL-8 and CXCL12 both in cardiac cells and human renal adenocarcinoma cells that are involved in cell death and heart failure as well as in cancer cell survival and resistance to apoptosis." (PMID 34178667, 2021). "Since β-ARs play a central role in heart failure pathogenesis via their modulation of calcium channel activity, a detailed analysis of the CXCL12/CXCR4 and/or CXCL12/CXCR7 relationship is warranted." (PMID 31071921, 2019). "Finally, high CXCL12 plasma levels are found in patients with hypertrophic cardiomyopathy, LVH, and heart failure, and CXCL12-dependent fibrocyte migration increases when diffuse fibrosis is present." (PMID 27525724, 2016). "It was found that CXCL12_CXCR4 was highly expressed in each stage of cardiac hypertrophy, indicating that endothelial cells played a crucial role in myocardial remodeling by secreting some chemokines and cytokines and regulating immune cell chemotaxis in heart failure." (PMID 36805782, 2023). "It has been demonstrated that patients with cardiac failure have increased levels of CXCR4 expression and its ligand CXCL12/SDF1." (PMID 33924458, 2021). "The modules related to germ cell migration and disrupted cellular calcium ion homeostasis were solely detected in heart failure arising from ISCM, with increased CXCR4, CCL5, and CXCL12." (PMID 29160422, 2017).
brain tumor (24 papers, 2008 to 2025). "Under certain pathological situations, including HIV 1-associated dementia, brain tumor, ischemia and neuroinflammation, CXCL12 expression may be briefly upregulated." (PMID 24932250, 2014). "High expression levels of CXCR4 and its ligand, the chemokine stromal cell-derived factor 1-α (SDF1-α = CXCL12), usually indicate a poor prognosis for patients with brain tumors." (PMID 32410920, 2020). "To clarify the mechanism of elevated CCL5 and CXCL12 levels in brain tumour tissues, we observed the activation of NF-κB in these tissues using western blot analysis." (PMID 27417157, 2016). "The significance of the expression and function of the CXCL12/CXCR4 axis in brain tumors has been intensely investigated in adult and children GBM, astrocytoma, medulloblastoma, oligodendroglioma, and oligodendroastrocytoma." (PMID 24904289, 2014). "Similar to its effects within germinal niches like the bone marrow and external granule cell layer of the developing cerebellum, CXCL12 chemo-attracts brain tumor cells to the peri-endothelial cell space and stimulates their growth within that domain." (PMID 22427929, 2012). "Together, these studies underscore the potential complexity of CXCL12 effects on brain tumor growth and the possibility for multiple mechanisms of CXCR4 antagonist action." (PMID 22427929, 2012). "Furthermore, the anti-CXCL12 aptamer NOX-A12 inhibits brain tumor recurrences after irradiation in rats." (PMID 26396176, 2015). "Relevant to brain tumors, endothelial cell CXCL12 could directly regulate tumor growth and spread, promote angiogenesis and/or regulate immune response to tumors." (PMID 22427929, 2012). "This was corroborated by the ability of the CXCL12 antagonist NOX-A12, to control autochthonous brain tumors in rats." (PMID 30813533, 2019). "We found that in addition to the chemokines secreted by engrafted stem cells, brain tumours derived from these grafts also produced high levels of CCL5 and CXCL12." (PMID 27417157, 2016). "As it was detailed above, despite being ELR (-) chemokine, CXCL12 acts as pro-angiogenic factor and stimulates VEGF expression, which could be a potential explanation for enhanced invasiveness of brain tumor." (PMID 32456359, 2020). "Several reports showed that the treatment with VEGFR inhibitor determined the activation of CXCL12/CXCR4 pathway, increasing circulating CXCL12 levels and CXCR4+ cells and the infiltration of myeloid BMDC in brain tumors and promoting angiogenesis, tumor growth, and metastasis." (PMID 26880981, 2016). "Serum CCL5 and CXCL12 levels in mice with brain tumours were obviously higher than those in mice without tumour formation and were positively correlated with the malignant grades of the tumours (P < 0.05)." (PMID 27417157, 2016). "Targeting the ligand, CXCL12, rather than its receptor, CXCR4, NOX-A12 is another inhibitor of the axis that is to be tested in brain tumors in combination with radiotherapy." (PMID 30813533, 2019).